INS (insulin)
Diseases named in the same sentence as INS in open-access papers (continued):
Sharing a sentence is not in itself a finding about the gene and the disease.
diabetes (continued). "For example, automated insulin delivery systems, such as closed-loop insulin pumps, are significant advancements in diabetes management." (PMID 40126308, 2025). "In diabetes, the structure of pancreatic islets and the physiological function of insulin-secreting cells are markedly impaired." (PMID 40806520, 2025). "Models were adjusted for index date, sex, age at index date, continuous BMI, insulin use, presence of diabetes-related end-organ complications, and median household income." (PMID 41209894, 2025). "Essential diabetes management services—including HbA1c testing, insulin provision, and glucose monitoring—are often unavailable, forcing patients to seek routine monitoring and complication treatment at district or provincial hospitals." (PMID 41080869, 2025). "This outcome differs from the results obtained in similar studies; but is similar to others which showed low adherence among diabetes patients on insulin alone." (PMID 39854487, 2025). "Several clinical and psychosocial factors have been associated with higher levels of diabetes distress, including insulin use, recent hypoglycemic episodes, diabetes complications such as retinopathy, and limited family or social support." (PMID 41288826, 2025). "Understanding the complexities of INS folding and the factors that contribute to misfolding offers opportunities for therapeutic development in diabetes." (PMID 40052150, 2025). "At 23, she was diagnosed with type 1 diabetes mellitus on the basis of significant hyperglycaemia and biochemical ketosis, and a basal bolus insulin regimen was initiated." (PMID 41367451, 2025). "RNF180-related genes can be categorized into gastric acid and insulin section, muscle and cardiomyopathy, glycoprotein binding, collagen and extracellular matrix, fat digestion and diabetes, PPAR signal pathway and peptidase activity." (PMID 40331188, 2025). "In animal experiments, short-term exposure to TCDD improves insulin sensitivity, whereas chronic exposure induces IR and diabetes, highlighting the complexity of the dose–response relationship." (PMID 41488239, 2025). "Of relevance, repeated subcutaneous injections of an insulin peptide delayed the onset of diabetes in prediabetic individuals for at least 1 year." (PMID 40430900, 2025). "In conclusion, this meta‐analysis suggests that once‐weekly insulin in Type 1 Diabetes Mellitus offers a nuanced alternative to daily insulin, with modest differences in glycemic control and notable safety considerations." (PMID 40186384, 2025). "In an experimentally induced diabetes model, resveratrol increased insulin sensitivity via WAT's normalization of visfatin and vaspin secretion." (PMID 40195898, 2025). "The evolution of microneedle design from solid to dissolvable forms broadens their utility from mere drug delivery to complex sensing and therapeutic applications, including insulin delivery for diabetes management, vaccination, and gene therapy." (PMID 39887601, 2025). "In this nationally representative cohort study using Medicare 2016 to 2020 data, CGM use was associated with a lower risk of all-cause hospitalization and mortality compared with prevalent SMBG users in insulin-treated older adults with diabetes and ADRD." (PMID 41329488, 2025). "Diabetes results from either insufficient insulin production by the pancreas or the inability of the body cells to utilize the insulin that is produced." (PMID 39888910, 2025). "The patient was cognitively intact, fully independent in daily living activities, and demonstrated a good understanding of diabetes self-management tasks, including glucose monitoring and insulin administration." (PMID 41473654, 2025). "Ultimately, only through multidisciplinary, multifaceted, and multicenter collaboration can the safety and efficacy of insulin therapy be continuously improved to better serve the vast majority of diabetes patients." (PMID 40997126, 2025).
diabetes (continued). "Those on insulin, oral hypoglycemic agents, or combination therapy had significantly lower physical QoL compared to patients managing diabetes through diet alone." (PMID 41464418, 2025). "Diabetes mellitus (DM) represents a spectrum of chronic metabolic disorders characterized by hyperglycemia resulting from defects in insulin secretion, insulin action, or, frequently, a combination of both." (PMID 41306154, 2025). "Second, during the study period, child healthcare, insulin and diabetes devices were heavily subsidised or provided free of charge in Sweden." (PMID 40781566, 2025). "Diabetes is a chronic metabolic disease characterized by abnormally elevated blood glucose levels, mainly driven by insufficient insulin secretion and/or impaired insulin action, leading to disorders of carbohydrate, fat and protein metabolism." (PMID 41001679, 2025). "Our results confirmed the successful establishment of diabetes subtypes within the FoCus cohort, reflecting similar patterns of disease severity, insulin sensitivity, -resistance and age as observed in the ANDIS cohort." (PMID 40022072, 2025). "In particular, combinations such as insulin-treated diabetes with hyperthyroidism included fewer than 60 patients, limiting the ability to detect associations or generalize findings." (PMID 41153651, 2025). "At the national level, there is the voluntary register of the National Diabetes Services Scheme (NDSS), which is estimated to hold information on 80–90% of Australians with insulin-treated diabetes." (PMID 40240222, 2025). "The war, restrictions on movement, and economic hardship in Palestine limit access to critical diabetes care services, like insulin, glucose monitoring devices, and specialized consultations that are essential for good health." (PMID 41216603, 2025). "Conventional diabetes treatments, such as insulin injections for type 1 diabetes mellitus (T1DM) and oral medications for T2DM, remain fundamental." (PMID 40742490, 2025). "GPS also improves insulin sensitivity in diabetes and inhibits tumor cell proliferation and migration." (PMID 41378205, 2025). "Targeted education is essential to improve safe insulin practices and reduce diabetes‐related complications." (PMID 41306599, 2025). "In older adults, propolis aids in reducing body fat and oxidative stress, while in metabolic disorders like PCOS and diabetes, it improves insulin sensitivity and lipid profiles." (PMID 40421039, 2025). "Oral delivery of DNA and genes is also a novel approach for diabetes treatment, providing a less invasive alternative to injections by introducing genes to enhance insulin production or glucose regulation." (PMID 40352348, 2025). "Earlier studies with (P3)PP in a rodent model of obesity-diabetes demonstrated treatment-induced preservation of pancreatic islet morphology and enhanced insulin secretion." (PMID 40362452, 2025). "Type 2 diabetes mellitus (T2D) is a chronic metabolic disorder characterized by elevated blood glucose levels due to insulin resistance (IR), a condition in which insulin-sensitive cells lose their ability to effectively respond to the hormone." (PMID 40065340, 2025). "Insulin therapy is used in their diabetes lifetime by nearly all people with type 2 diabetes (T2DM), as well as in all people with type 1 diabetes (T1DM)." (PMID 40035222, 2025). "Nonetheless, most dogs with diabetes remain insulin-dependent, aligning more closely with human T1DM." (PMID 41012437, 2025). "Vildagliptin added to premixed insulin effectively lowers blood glucose levels and reduces glycemic variability in patients with type 2 diabetes mellitus." (PMID 40620795, 2025). "The findings highlight the significant role of Kv2.2 channels in the regulation of β-cell repetitive firing and insulin secretion, and contribute to the understanding of the molecular basis of β-cell dysfunction in diabetes." (PMID 40028769, 2025).
diabetes (continued). "On the other hand, a significant increase in PDX1 was observed in the insulin-treated group as compared to the diabetes-untreated group." (PMID 40536613, 2025). "Currently, modern medical treatments for diabetes include insulin, insulin sensitizers, and α-glucosidase inhibitors, but the disease is prone to relapse." (PMID 41356003, 2025). "Diabetes self-management encompasses a range of behaviors, including but not limited to checking blood glucose, taking medications (including insulin), following dietary guidelines, engaging in physical activity, and engaging in foot care." (PMID 40564574, 2025). "Hyperglycemia is commonly recognized as a manifestation of diabetes, particularly type 2 diabetes, where blood glucose levels cannot be effectively regulated owing to insufficient insulin secretion or impaired cellular responses to insulin." (PMID 40948873, 2025). "In patients with obesity and diabetes, altered acetylation or phosphorylation of mTOR disrupts its role in insulin signaling, impairing glucose metabolism and contributing to insulin resistance." (PMID 40547482, 2025). "Advances such as continuous glucose monitoring and automated insulin delivery systems and insights from genomics and metabolomics are revolutionising diabetes care." (PMID 40553147, 2025). "Compared with standard formulas, diabetes-specific formulas offer significant advantages in lowering blood glucose, insulin requirements, and infection risks." (PMID 39940308, 2025). "In humans, the progression from pre-diabetes to diabetes requires, in addition to glycemic changes and changes in insulin function, a significant reduction in the mass of functional beta cells." (PMID 40426986, 2025). "Metabolic disorders, including diabetes and obesity, are conditions characterized by abnormalities in the body’s metabolic processes, leading to issues like insulin resistance, increased fat accumulation, and heightened cardiovascular risk." (PMID 41394126, 2025). "For instance, in the adult post–lung transplant routine clinic protocol order set, the system suggested considering medications such as metformin or insulin for managing posttransplant diabetes." (PMID 40986301, 2025). "For example, in alcohol-related liver disease, the development of diabetes can occur from excessive alcohol consumption by reducing the insulin-mediated glucose uptake and damaging pancreatic islet cells." (PMID 40491591, 2025). "In recent years, β-cell deficiency and dysfunction have been identified as key factors affecting both insulin production and resistance, contributing to the development of type 1 diabetes mellitus (T1DM) and type 2 diabetes mellitus (T2DM)." (PMID 40866949, 2025). "For GCIH management, the Joint British Diabetes Societies (JBDS) and the American Diabetes Association recommend the sulfonylurea (SU) agent gliclazide and Neutral Protamine Hagedorn (NPH) insulin." (PMID 41464548, 2025). "In this review, we discuss how specific PTMs in insulin target tissues and pancreatic beta cells contribute to the development and progression of diabetes and consider their potential as therapeutic targets." (PMID 41373704, 2025). "Insulin resistance and decreased insulin secretion are the main pathophysiological processes that lead to diabetes." (PMID 41323015, 2025). "Diabetes mellitus is a persistent and progressive metabolic disease characterized by high blood glucose levels due to a defect in insulin production or a defect in insulin action, or both." (PMID 40370420, 2025). "With its natural origin, versatility in formulation, and minimal side effects, gelatin is poised to play a significant role in advancing insulin delivery technologies and improving the management of diabetes." (PMID 40352348, 2025). "HIIT, characterized by repeated short bouts of vigorous activity interspersed with recovery periods, exerts unique metabolic effects that significantly improve insulin-related parameters in individuals with type 2 diabetes mellitus." (PMID 41295324, 2025).
diabetes (continued). "Diabetes mellitus promotes oxidative stress through multiple interlinked mechanisms, particularly involving pancreatic β-cell dysfunction, insulin resistance, and mitochondrial overactivation." (PMID 41154538, 2025). "While both concepts are applied across various chronic conditions, their operationalisation in diabetes involves unique behaviours such as blood glucose monitoring, carbohydrate counting, insulin titration, and foot care." (PMID 40489012, 2025). "Recent studies show that replacing palmitic acid with oleic acid can improve insulin sensitivity and protect against diabetes." (PMID 41373632, 2025). "Diabetes, a metabolic disorder characterized by hyperglycemia resulting from insulin insufficiency or impaired insulin sensitivity, is one of the major global health challenges." (PMID 41301913, 2025). "Research indicates that diets rich in starch and monounsaturated fats can enhance insulin sensitivity, and dietary management is a first-line strategy for controlling dyslipidemia in patients with diabetes." (PMID 41333960, 2025). "Diabetes in WS1 typically has an early-onset, progresses slowly, and is characterized by insulin deficiency, low insulin requirement, and a lower incidence of chronic complications compared to type 1 autoimmune diabetes." (PMID 40988749, 2025). "Diabetes mellitus (DM) refers to several disorders of carbohydrate metabolism characterized by hyperglycemia, which are associated with either a relative or an absolute impairment of insulin secretion, with varying degrees of insulin resistance." (PMID 40204274, 2025). "A low-grade inflammatory condition by interfering with insulin signaling and inducing insulin resistance also plays a crucial role in obesity and diabetes." (PMID 39940300, 2025). "It promotes fatty acid synthesis and storage, enhances insulin sensitivity, and modulates inflammatory responses, making it a key target in the treatment of diabetes and metabolic syndrome." (PMID 41200186, 2025). "Diabetes induced hyperglycemia and reduction in circulating insulin levels, in parallel to an increase in plasma corticosterone levels in Swiss-Webster mice, compared to non-diabetic mice." (PMID 40496562, 2025). "For Diabetes management, AI-based wearables, including continuous glucose monitoring sensors, AI-driven insulin pumps, and closed-loop systems, are reviewed." (PMID 41294766, 2025). "Diabetes is a chronic metabolic disorder characterized by high blood sugar levels due to the body's inability to produce sufficient insulin (type 1 diabetes [T1DM]) or to effectively use the insulin it produces (type 2 diabetes [T2DM])." (PMID 40989572, 2025). "Inflammatory cytokines, e.g., IL-1β, impair β-cell function and survival, contributing to diabetes pathogenesis by inducing stress, altering gene expression, driving dedifferentiation, and reducing insulin production." (PMID 41120257, 2025). "In the CRISTAL trial, 95 pregnant females with diabetes were randomly assigned to AHCL therapy using Minimed 780G with SmartGuard algorithm or standard insulin therapy." (PMID 40988749, 2025). "Responders exhibited restored glucose- and arginine-stimulated acute insulin secretion, directly linking beta cell recovery to diabetes reversal." (PMID 40768044, 2025). "Inadequate dietary intake of essential nutrients can worsen insulin dysregulation and contribute to the progression of diabetes-related complications and MetS." (PMID 40735237, 2025). "The updated guidelines systematically review evidence‐based recommendations for managing diabetes in the elderly, emphasizing the benefits of modern monitoring and insulin delivery technologies." (PMID 41180388, 2025). "Therapeutic management focuses on the treatment of comorbid conditions that include fenofibrate and statins for dyslipidemia and metformin, insulin, and pioglitazone for diabetes mellitus." (PMID 40718185, 2025).
diabetes (continued). "Much of the improvement in life expectancy over the past decades can be attributed to advances in diabetes treatment, including intensive insulin therapy, better glucose monitoring, and management of cardiovascular risk factors." (PMID 41323965, 2025). "Diabetes mellitus is a group of metabolic disorders characterized by hyperglycemia, which is due to defects in insulin secretion, insulin action, or both." (PMID 40585884, 2025). "Responsibility for managing diabetes and insulin during admission was generally held by nursing and medical staff." (PMID 40324886, 2025). "The National Diabetes Inpatient Audit (NaDIA) reviews several aspects of care including medication errors, inappropriate use of insulin infusions, harms such as in‐hospital hypoglycaemia, hospital acquired diabetic ketoacidosis and foot lesions." (PMID 39432570, 2025). "Type 2 diabetes mellitus is characterised by insulin resistance or insufficient insulin production to meet physiological demand." (PMID 41170150, 2025). "Of these study patients, treated for 638 target lesions, 165 (34.7%) were women and 122 (25.7%) were known to have diabetes, of whom 39/122 (32.0%) were treated with insulin." (PMID 40035811, 2025). "Electronic chart data from 295 diabetes specialist care centres in Italy showed that despite treatment with insulin, 16.1% of patients have an HbA1c ≥ 9.0%." (PMID 40277315, 2025). "Diabetes is a metabolic disorder characterized by persistent hyperglycemia due to impaired insulin secretion or cellular responsiveness." (PMID 40777990, 2025). "Diabetes care has been revolutionized by advances in glucose sensors and insulin pump technology, with recent standards of care emphasizing their early use in the management of people on insulin therapy." (PMID 41473236, 2025). "In general, the principal aims of the treatment of diabetes are to reduce blood glucose concentrations, improve insulin sensitivity, and preserve pancreatic β cells, and resveratrol has been shown to have all of these effects." (PMID 41020857, 2025). "Insulin resistance (IR) is a hallmark of type 2 diabetes mellitus (T2DM), characterized by reduced sensitivity and responsiveness to insulin in peripheral tissues such as the liver and muscles, ultimately leading to dysregulation of blood glucose levels." (PMID 40005141, 2025). "Disruption of insulin signaling, as seen in insulin resistance and type 2 diabetes mellitus, leads to impaired glucose uptake and dysregulated lipid metabolism, which contributes to metabolic dysfunction and hyperglycemia." (PMID 40989682, 2025). "Despite the uncertainty around these thresholds, they have been successfully utilised in studies, for example, to clarify diabetes aetiology and in some cases, have allowed for successful insulin withdrawal." (PMID 39797595, 2025). "Among these, AKS-218d, a recombinant fusion insulin analog, has been evaluated in dogs with diabetes and demonstrated sustained glycemic control with a single subcutaneous injection per week." (PMID 41012437, 2025). "That is, GHRKO mice have reduced body size, improved insulin sensitivity, resistance to diet-induced diabetes, lower cancer incidence, and better cognitive function in later life." (PMID 41350448, 2025). "The most frequent precipitating factor for diabetic ketoacidosis (DKA) in patients with type 1 diabetes mellitus (T1DM) is missed or inadequate insulin administration." (PMID 41149081, 2025). "We observed marked hyperglycaemia and glycated haemoglobin accumulation during 4-week diabetes, decreased insulin level in the blood plasma, increased insulin resistance (the HOMA-IR value), anaemia and hyperproteinaemia." (PMID 40161891, 2025). "Type 1 diabetes mellitus is characterized by the autoimmune destruction of insulin‐secreting beta cells in the pancreas, and blood glucose levels of patients with diabetes mellitus are managed through exogenous insulin therapy to maintain normoglycemia." (PMID 41438817, 2025).